SNX20 (sorting nexin 20)
Description:
May play a role in cellular vesicle trafficking. Has been proposed to function as a sorting protein that targets SELPLG into endosomes, but has no effect on SELPLG internalization from the cell surface, or on SELPLG-mediated cell-cell adhesion.
Synonyms: SLIC-1; SLIC1
Tractability: Antibody: UniProt places it where antibodies can reach, with high confidence; its Gene Ontology location is reachable by antibodies, with medium confidence. PROTAC: its protein half-life has been measured.
Gene: Protein-coding gene on chromosome 16 (50,666,300 to 50,681,743, reverse strand). Ensembl gene ENSG00000167208.
Subcellular location: Early endosome membrane; Cell membrane; Cytoplasm; Nucleus
Subcellular location (Human Protein Atlas): Nucleoplasm
Gene Ontology:
Molecular function: protein binding; phosphatidylinositol phosphate binding; phosphatidylinositol-3-phosphate binding; phosphatidylinositol-4,5-bisphosphate binding; phosphatidylinositol binding
Biological process: protein transport
Cellular component: early endosome membrane; cytoplasm; nucleus; plasma membrane
Genetic constraint (gnomAD): Loss-of-function variants: 24 observed, 23.19 expected, observed/expected ratio (o/e) 1.03, 90% interval 0.75 to 1.46. The upper end of that interval is the gene's LOEUF score, 1.46, which puts it in group 6 of 6, group 1 being the genes least tolerant of losing a copy. Missense variants: 433 observed, 389.15 expected, observed/expected ratio (o/e) 1.11, 90% interval 1.03 to 1.21. Synonymous variants: 206 observed, 171.19 expected, observed/expected ratio (o/e) 1.2, 90% interval 1.07 to 1.35.
Homologues: Orthologues: chimpanzee SNX20 (97% identical), macaque SNX20 (97% identical), rabbit SNX20 (83% identical), mouse Snx20 (77% identical), pig SNX20 (77% identical), guinea pig SNX20 (76% identical), rat Snx20 (75% identical), dog SNX20 (70% identical), zebrafish snx20 (40% identical), Drosophila melanogaster Snx21 (26% identical). Paralogues in human: SNX21 (34% identical).
Diseases named in the same sentence as SNX20 in open-access papers:
SNX20 is named in the same sentence as 13 diseases in open-access papers, as found by Europe PMC text mining. Sharing a sentence is not in itself a finding about the gene and the disease. The quoted sentences say what the papers report.
lung adenocarcinoma (4 papers, 2021 to 2026). A carcinoma that arises from the lung and is characterized by the presence of malignant glandular epithelial cells. "In contrast, SNX20 expression predicts a positive response to PD-1 inhibitors in lung adenocarcinoma." (PMID 41487280, 2026). "Previous reports have suggested that SNX20 expression is strongly correlated with immune infiltration levels in lung adenocarcinoma." (PMID 35771139, 2022). "In this study, we aimed to investigate the role of SNX20 in Lung adenocarcinoma progression and tumor-infiltrating lymphocytes." (PMID 34604311, 2021). "Collectively, our findings demonstrate the suppressor roles of the SNX20AR/miRNA-301a-3p/SNX20 axis in Lung Adenocarcinoma, represent that SNX20 have the potential of as an effective therapeutic target in future." (PMID 34604311, 2021). "Here, we employ the TCGA, GEO and CCLE databases to examine the expression of SNX20 in human varies cancer, the results shown that SNX20 is down-regulated in lung Adenocarcinoma, SNX20 level was significantly positive correlated with poor prognosis and lung cancer immune cell infiltration." (PMID 34604311, 2021). "Also the high expression of SNX20, which is connected with SASH3 and CD53 through the focal adhesion-encoding gene LPXN, has been associated with immune-active TIME and better OS in lung adenocarcinoma patients." (PMID 39107857, 2024).
Crohn disease (2 papers, 2015 to 2016). A gastrointestinal disorder characterized by chronic inflammation involving all layers of the intestinal wall, noncaseating granulomas affecting the intestinal wall and regional lymph nodes, and transmural fibrosis. "Hence, SNX20 may contribute to Crohn’s disease susceptibility associated with variation at this locus." (PMID 25717144, 2015). "rs9302752 lies between NOD2 and SNX20 in a susceptibility locus for leprosy but not Crohn’s disease, and has been presumed to predispose to leprosy via altering NOD2 expression." (PMID 27015630, 2016).
diabetes (2 papers, 2021 to 2022). "Microarray analysis of the PBMC dataset (Cohort 1), identified FcER1, TRPC3, SNX20, FAM20A, and SLC12A7 as genes showing increased expression with the severity of diabetes." (PMID 34925339, 2021).
lung carcinoma (2 papers, 2021 to 2023). "Next, we employed the Starbase and Kmplot databases analysis the expression and prognosis of SNX20 in Lung cancer." (PMID 34604311, 2021). "We identified that SNX20AR/miRNA-301a-3p mediated decreased of SNX20 correlated with lung cancer progression and cancer immune infiltration in LUAD." (PMID 34604311, 2021). "Furthermore, we identified that SNX20AR/miRNA-301a-3p mediated decreased of SNX20 correlated with lung cancer progression and cancer immune infiltration in LUAD." (PMID 34604311, 2021). "We further explored the expression of SNX20 and the different immune cells infiltration whether influence the prognosis of lung cancer patients." (PMID 34604311, 2021).
acute myeloid leukemia (1 paper, 2022). Acute myeloid leukemia (AML) is a group of neoplasms arising from precursor cells committed to the myeloid cell-line differentiation. "SNX20 participates mainly in the acute myeloid leukemia, NOD-like receptor signaling pathway, the mTOR signaling pathway." (PMID 35771139, 2022).
glioma (1 paper, 2022). A benign or malignant brain and spinal cord tumor that arises from glial cells (astrocytes, oligodendrocytes, ependymal cells). "Finally, we show that SNX20 expression was positively associated with the immune modulator in glioma." (PMID 35771139, 2022). "In this study, we found that SNX20 was highly expressed in glioma and correlated with unfavourable clinical outcomes." (PMID 35771139, 2022). "The results of the Cox regression analysis revealed that SNX20 was an independent factor for the prognosis of low-grade glioma." (PMID 35771139, 2022). "In this study, we determined that SNX20 was up-regulated in the diverse human cancers, especially in glioma." (PMID 35771139, 2022). "This study firstly uncover that the potential biological functional of SNX20 in the progression of LGG, which represents a potential diagnostic and prognostic biomarker for glioma in the future." (PMID 35771139, 2022). "Cox regression analysis confirmed that SNX20 was an independent prognosis factor for glioma prognosis." (PMID 35771139, 2022). "Depletion of SNX20 evidently inhibited glioma cell growth and migration abilities." (PMID 35771139, 2022). "Furthermore, we determined that SNX20 was increased in glioma tissue compared to the control group based on TCGA and GEO datasets." (PMID 35771139, 2022). "Depletion of SNX20 significantly inhibits glioma cell proliferation and migration abilities." (PMID 35771139, 2022). "Importantly, we found that SNX20 was highly expressed in glioma cell lines." (PMID 35771139, 2022). "SNX20 could be a novel potential target for diagnosis and treatment of glioma." (PMID 35771139, 2022). "However, it remains unclear the biological function and immune infiltration role of SNX20 in glioma progression." (PMID 35771139, 2022).
non-small cell lung carcinoma (1 paper, 2022). A group of at least three distinct histological types of lung cancer, including non-small cell squamous cell carcinoma, adenocarcinoma, and large cell carcinoma. "Above results show that SNX20 functions as a tumor suppressor in non-small cell lung cancer." (PMID 35771139, 2022).
cancer (4 papers, 2021 to 2025). A tumor composed of atypical neoplastic, often pleomorphic cells that invade other tissues. "We used the TCGA and the Genotype-Tissue Expression (GTEx) databases to explore the expression of SNX20 in various cancers, Results showed that SNX20 differentially expressed in various human cancers." (PMID 35771139, 2022). "The correlation between SNX20 expression and different tumor lymphocyte infiltration in human cancer by perform the TISIDB databases analysis." (PMID 34604311, 2021). "In summary, these results demonstrate that SNX20 was significantly related to diverse drug sensitivity in the different cancer cell lines." (PMID 34604311, 2021). "In this study, we analysis the SNX20 expression in human cancers, the results shown that SNX20 was elevated in the nine cancers." (PMID 34604311, 2021). "We employ the GEPIA tools to examine the relationship between the expression of SNX20 and the human cancers pathological stage." (PMID 34604311, 2021). "Increasing evidence has demonstrated that SNX20 plays crucial roles in the progression of human cancer." (PMID 34604311, 2021). "Above all, our findings indicated that the SNX20 may plays different roles in the progression of different cancers." (PMID 34604311, 2021). "The prognostic value of SNX20 expression in human cancers was analyzed by several databases." (PMID 34604311, 2021). "Above results suggested that SNX20 may plays oncogene roles in the cancer progression, so we next explored the correlation between SNX20 expression and different drug sensitivity in different cancer cell lines from the GDSC and CTRP database." (PMID 34604311, 2021). "Therefore, targeting SNX20 may be an alternative strategy for cancer therapy." (PMID 35771139, 2022). "In order to examine the mRNA of SNX20 expression pattern in multifarious cancer, we employed the TIMER tools to analysis the expression of SNX20, the result shown that SNX20 was low expression in LUAD, LUSC, and PAAD, higher expression was observed in BRCA, CHOL, ESCA, GBM, HNSC, KIRC, and KIRP." (PMID 34604311, 2021).
tumor (4 papers, 2021 to 2025). "SNX20, encoding the sorting nexin 20 protein, plays a crucial role in the immune cell infiltration and regulates various immune molecules in the tumor microenvironment." (PMID 38020709, 2023). "Finally, our work demonstrates that SNX20 was further implicated in alteration of the tumor microenvironment." (PMID 34604311, 2021). "The results suggested that SNX20 was positively with the 28 tumor immune infiltrating cell, immune regulator and MHC molecular." (PMID 34604311, 2021). "In addition, we also find the expression of SNX20 was decreased with the elevation of stage nodal metastasis and tumor stage." (PMID 34604311, 2021). "Indeed, the WGCNA of TCGA-LUAD cohort revealed that patients with this tumor phenotype had down-regulated an extensive gene network led by SASH3 and including IKZF1, IL10RA, CD53 and SNX20, all involved in immune activation." (PMID 39107857, 2024).
infection (1 paper, 2023). The state of being infected such as from the introduction of a foreign agent such as serum, vaccine, antigenic substance or organism. "We therefore hypothesize that variants of SNX20 may associated with the immune cell infiltration during the infection of M. leprae." (PMID 38020709, 2023).
SNX20 also shares sentences with these, for which no sentence is quoted: Alzheimer disease (1 paper); cardiovascular disease (1); leprosy (1).